MSLN (mesothelin)
Diseases named in the same sentence as MSLN in open-access papers (continued):
Sharing a sentence is not in itself a finding about the gene and the disease.
pancreatic cancer (continued). "Rescent studies have shown that overexpression of mesothelin significantly increased tumor cell proliferation, and downregulation of mesothelin inhibited cell proliferation in pancreatic cancer cells, but its exact function and mechanism remains unclear." (PMID 23034174, 2012). "Interestingly, tumors with constitutive activation of the Wnt signaling pathway, such as ovarian and pancreatic cancers, have high MSLN expression." (PMID 22485139, 2012). "This study validates MUC1 and MSLN as biomarkers of aggressive pancreatic cancer biology." (PMID 22792233, 2012). "Targeting mesothelin by shRNA is the important method for pancreatic cancer therapy." (PMID 23034174, 2012). "To help find additional factors which might affect the therapy, we examined the resistance of MSLN-overexpressing pancreatic cancer cell lines to TNF-α-induced growth inhibition/apoptosis." (PMID 21880146, 2011). "Our study may indicate a very important survival axis of MSLN-expressing pancreatic cancer cells in midst of inflammatory cytokines abundant in this cancer." (PMID 21880146, 2011). "Consistently, a significant correlation was observed between the expression level of MSLN and the apCAF score, which is calculated using single‐sample Gene Set Enrichment Analysis (ssGSEA) with top20 marker genes derived from apCAF cluster, within TCGA pancreatic cancer samples (p = 0.00027)." (PMID 39887656, 2025). "In addition, pancreatic cancer cells secrete small extracellular vesicles (EVs) carrying PD-L1 and MSLN, which not only reduce antigen density but also interfere with the proper targeting of endogenous T cells and MSLN-CAR-T cells." (PMID 40072049, 2025). "One study found that treating pancreatic tumors, characterized by their dense desmoplastic stroma, in mice with FAP-targeting CAR T-cells reduced the integrity of the desmoplastic matrix, thereby making the tumors more susceptible to infiltration by CAR T-cells targeted against mesothelin, a TAA." (PMID 41019052, 2025). "Accumulating evidence demonstrates that MSLN exhibits minimal expression in normal pancreatic tissues or adjacent non-malignant tissues, whereas it demonstrates robust expression in the majority of pancreatic cancer tissues, with this differential expression pattern being statistically significant." (PMID 41400642, 2025). "Moreover, combining cGAMP with anti-MSLN CAR-NK-92 cells could enhance pancreatic cancer cells’ cytotoxicity and anti-tumor activity, potentially forming a unique clinical treatment approach." (PMID 38694508, 2024). "We concluded that MSLN could promote intercellular-matrix adhesion in pancreatic cancer." (PMID 38628720, 2024). "Thus, this immune competent mouse model replicates the poor in vivo therapeutic efficacy reported in early phase clinical trials of standard anti-mesothelin CAR T cells in pancreatic cancer, making it an ideal model in which to test enhancement of the CAR T cells with synthetic IL-2 circuits." (PMID 36520915, 2022). "The current review study identifies 22 IHC biomarkers as diagnostic tools for pancreatic cancer that embrace: Pentraxin-3, ENO1, REG4, POSTN, CA125, CA242, Galectin-1, Galectin-9, Maspin, pVHL, MUC1, MUC5AC, THBS2, LTBP2, CPA4, IMP3, CD13, Dkk1, KOC, S100P, Mesothelin, PAM4." (PMID 34988027, 2021). "Thus, mesothelin might be an attractive therapeutic target for pancreatic cancer, and we focused on this protein for developing a cancer vaccine using an epitope peptide." (PMID 30140382, 2018). "Thus, mesothelin might be an attractive target for the development of novel cancer treatments for pancreatic cancer." (PMID 30140382, 2018). "Thus, mesothelin-10-5 peptide-specific CTLs might exert an antitumor effect against mesothelin-expressing pancreatic cancer cells in HLA-A24-positive patients." (PMID 30140382, 2018). "Thus, MSLN is a possible biomarker for pancreatic cancer and target for T-cell based immunotherapy." (PMID 24520352, 2014).
pancreatic cancer (continued). "Mesothelin (MSLN) is up-regulated in many tumors, including pancreatic tumors, making it a promising therapeutic target." (PMID 42125244, 2026). "The results showed that MSLN overexpression significantly reduced CD3+CD8+ T cell infiltration (p = 0.001) in pancreatic cancer." (PMID 39887656, 2025). "Subsequently, we further validated the correlation between MSLN expression and CD3+CD8+ T cell infiltration in 30 paired pancreatic tumor tissues and adjacent tissues using multiple immunofluorescence technique on tissue microarrays." (PMID 39887656, 2025). "The targets of CAR-T cell clinical trials in the treatment of pancreatic cancer patients include EGFR, HER2, CD133, and mesothelin." (PMID 41417221, 2025). "The mRNA expression of Mesothelin was confirmed by in situ hybridization and RT‐PCR in resected PDAC and pancreatic cancer cell lines respectively." (PMID 39434498, 2025). "Mesothelin (MSLN) is a prominent target antigen for CAR T cell therapy due to its extensive expression in various solid tumors, including pancreatic cancer." (PMID 40366419, 2025). "n a mouse pancreatic cancer model, transduction of CXCR6 into CAR-T cells targeting mesothelin (CART-MSLN) promoted tumor rejection and durable remission." (PMID 41479900, 2025). "Bispecific antibodies, such as anti-CD3/mesothelin and CD3/claudin-18.2, have demonstrated potent cytotoxic activity in preclinical pancreatic cancer models and are progressing into early-phase clinical trials." (PMID 40895848, 2025). "MSLN expression increased in a MOI-dependent manner, with nearly 80% of cancer cells showing MSLN positivity after 18 h at a MOI of 1 in both pancreatic cancer cell lines." (PMID 40366419, 2025). "Taken together, our therapeutic strategy of combining MSLN‐targeted antibody with personalized neoantigen vaccine could provide a new perspective for improve therapeutic outcomes by efficiently relieving the immunosuppressive state of pancreatic cancer microenvironment." (PMID 39887656, 2025). "The resulting anti-MSLN DARPin, called M7A-DC, was conjugated to MMAE, a tubulin inhibitor, and tested in a preclinical pancreatic cancer model." (PMID 41335396, 2025). "Numerous clinical studies have identified specific targets, such as mesothelin (MSLN), CD133, Prostate stem cell antigen (PSCA), Claudin 18.2, and HER-2, for CAR-T immunotherapy in pancreatic cancer (PCA)." (PMID 38801637, 2024). "Here, we comprehensively and systematically explored potential roles of MSLN in chemoresistance and its relationship with proliferation, EMT and cancer stem cell traits of pancreatic cancer cells." (PMID 38628720, 2024). "Human pancreatic cancer cell lines ASPC-1 and Mia PaCa-2 with high and low expression of MSLN, respectively, were selected." (PMID 38628720, 2024). "We aim to investigate potential roles of MSLN in chemoresistance and its relationship with proliferation, epithelial-mesenchymal transition (EMT) and cancer stemness of pancreatic cancer cells." (PMID 38628720, 2024). "Therefore, MSLN could potentially trigger EMT in pancreatic cancer cells." (PMID 38628720, 2024). "An anti-mesothelin targeting ADC, BAY 94-9343, was used for the treatment of pre-clinical cancer models including pancreatic cancer." (PMID 37880707, 2023). "Li and coworkers in 2008 studied the effects of MSLN overexpression in pancreatic cancer preclinical models and developed a prototype of SHIV VLP vaccine displaying human MSLN (hMSLN)." (PMID 37629147, 2023). "Studies have shown that overexpression of MSLN can activate the PI3K pathway and induce drug resistance in pancreatic cancer cells." (PMID 35692779, 2022). "Overexpression of miR‐198 in pancreatic cancer cells inhibited tumour growth, metastasis, and promoted survival by directly targeting PBX‐1, MSLN, and VCP." (PMID 35068042, 2022).
pancreatic cancer (continued). "The cell surface glycoprotein, Mesothelin (MSLN), is overexpressed in many cancers, including pancreatic cancer, and is seen used as a potential anti-cancer drug target." (PMID 33632278, 2021). "MSLN immune-targeted therapy (mAbs, CAR-T, vaccine) has top notch potential, and many of them have entered clinical trials of pancreatic cancer and lung cancer." (PMID 35111680, 2021). "The overexpression of MSLN activates NFκB, MAPK, and PI3K pathways, leading to resistance of apoptosis in pancreatic cancer cells." (PMID 34326410, 2021). "Also, the enhancement of the hydrophilicity of the rest of the CDR residues could drastically increase the overall solubility of the optimized anti-MSLN antibodies, and thus substantially improve the efficacies of the ADCs in treating human gastric and pancreatic tumor xenograft models in mice." (PMID 34326410, 2021). "Mesothelin (MSLN), a glycoprotein membrane whose expression is limited to mesothelial cells, is overexpressed in most pancreatic cancers and is involved in tumor adhesion and dissemination, making it a robust therapeutic target." (PMID 32349216, 2020). "To explore the mechanistic link between MSLN and RARG expression, we utilized a panel of pancreatic cancer cell lines with a range of MSLN levels." (PMID 32616712, 2020). "Another anti-MSLN antibody, MMOT05530A, was radiolabeled with 89Zr for PET imaging of MSLN-expressing human pancreatic tumor xenografts." (PMID 33081383, 2020). "One intriguing observation qualifying its role as an antigen of interest is that mesothelin-specific CD4+ and CD8+ T cell reactivity is evident in patients with pancreatic cancer." (PMID 30319627, 2018). "Thus, we hypothesize that IL-21 exhibits a biologically relevant and generally positive effect on circulating immune cells in patients with pancreatic cancer, associated with expansion of certain TCR specificities, such as specific mesothelin epitopes, described in this report." (PMID 29854291, 2018). "Herein, we demonstrate, for the first time to our knowledge, that dCAR-modified T cell exerts effective and safe cytotoxicity for the treatment of pancreatic cancer cell expressing the tumor antigens CEA and MSLN in vitro and in vivo." (PMID 30103775, 2018). "In this study, we selected the pancreatic cancer cell line AsPC-1 as a target cell due to its high expression of both CEA and MSLN." (PMID 30103775, 2018). "Mesothelin (MSLN) is a membrane-anchored protein normally seen in mesothelial cells and is overexpressed in all pancreatic cancer tissue according to investigator Gregory L. Beatty, M.D., Ph.D., assistant professor of medicine." (PMID 28239502, 2017). "A recent study demonstrated that TIL expanded from pancreatic tumors recognized shared pancreatic tumor antigens, including NY-ESO-1, survivin, and mesothelin." (PMID 27777771, 2016). "MUC16 is significantly upregulated in pancreatic cancer and co-overexpressed with MSLN (Mesothelin) at the invading edge." (PMID 26555578, 2015). "Overexpression of the MSLN gene was shown to enhance interleukin (IL)-6 signaling, and to confer resistance to tumor necrosis factor (TNF)-α mediated apoptosis in pancreatic cancer cell lines." (PMID 25118887, 2014). "Mesothelin and PSCA have subsequently been utilised as adjuncts in diagnosis, as candidate serum biomarkers and as targets of pancreatic cancer immunotherapy." (PMID 18954444, 2008). "Based on this mechanism, the anti-MSLN-7 × 19 CAR-T cells constructed showed superior migration ability to traditional anti-MSLN CAR-T cells in vitro studies and demonstrated stronger infiltration and killing effects on MSLN-positive pancreatic cancer cell lines (AsPC-1) in xenograft models." (PMID 41400642, 2025).
pancreatic cancer (continued). "In conclusion, MSLN could induce chemoresistance by enhancing migration, invasion, EMT and cancer stem cell traits of pancreatic cancer cells." (PMID 38628720, 2024). "We concluded that MSLN could induce chemoresistance by enhancing migration, invasion, EMT and cancer stem cell traits of pancreatic cancer cells." (PMID 38628720, 2024). "Targeting MSLN could represent a promising therapeutic strategy for reversing EMT and chemoresistance in pancreatic cancer cells." (PMID 38628720, 2024). "A chimeric murine MSLN-VLP has been shown to break the tolerance to the murine MSLN self-antigen, as well as reduce tumor growth and prolong overall survival in an orthotopic pancreatic cancer model." (PMID 35214685, 2022). "In a phase I/II study on the efficacy of the MSLN-targeting recombinant immunotoxin, LMB-100, in combination with nab-paclitaxel for the treatment of advanced pancreatic cancer, a correlation between CA19-9 response to investigational treatment and MSLN expression was suggested." (PMID 36434635, 2022). "Mesothelin is a target molecule in several tumors and is also specifically overexpressed in pancreatic cancer cell lines (CAPAN1 and Hs766T) but not in the surrounding healthy tissues." (PMID 36136517, 2022). "At molecular level, the interaction of MSLN with CA-125/MUC16, which participates in cell-to-cell interactions enabling tumorigenesis and tumor proliferation, increases the motility and invasion of pancreatic carcinoma cells." (PMID 34326410, 2021). "Moreover, MSLN-specific CAR-T cell therapy resulted in the regression of human ovarian cancer in mice, as well as an anticancer response in patients with pancreatic cancer metastases." (PMID 32560392, 2020). "Interestingly, engineered T cells with a dual-receptor CAR (dCAR-T) exert high cytotoxicity against pancreatic tumor cells expressing tumor antigens, CEA and mesothelin, resulting in 80% apoptosis of tumor cell." (PMID 30987642, 2019). "We reported that MUC16 and mesothelin were overexpressed only in infiltrating pancreatic cancer cells but not in PanIN-3 cells or normal pancreatic tissues." (PMID 30140382, 2018). "For instance, Chimeric Antigen Receptor (CAR) T cells engineered to target a native protein mesothelin overexpressed on pancreatic cancer cells show significant anti-tumor activity independent of chemotherapy or radiation." (PMID 29320425, 2018). "The TfR, like MSLN, is expressed on the surface of KLM1 and other pancreatic cancer cell lines." (PMID 27999204, 2017). "For pancreatic cancer, PSCA, Tn glycan on the mucin 1 (MUC1), and mesothelin are all overexpressed." (PMID 28239502, 2017). "The K562 chronic myelogenous leukaemia cell line was used as a negative control, while the PaTu pancreatic cancer cell line served as positive control for mesothelin expression." (PMID 29113296, 2017). "The most advanced vaccine strategy for pancreas cancer is a combination of low dose cyclophosphamide with GVAX, composed of two irradiated GM-CSF secreting allogeneic pancreas cancer cell lines, followed by CRS-207, a live attenuated Listeria monocytogenes that secretes mesothelin." (PMID 28388966, 2017). "Mesothelin (MSLN) antigen is a biomarker for ovarian and pancreatic cancer." (PMID 28825646, 2017). "Stable overexpression of mesothelin in a pancreatic cancer cell line did not increase cell proliferation or anchorage-independent growth in vitro, suggesting that mesothelin is not necessarily a tumor progression factor as previously reported." (PMID 26931187, 2016). "Stable overexpression of mesothelin in a pancreatic cancer cell line did not increase cell proliferation or anchorage-independent growth in vitro, suggesting that mesothelin is not necessarily a tumor progression factor." (PMID 26931187, 2016).
pancreatic cancer (continued). "This tendency is similar to the previous immunohistochemistry reports that the expression of MSLN was strongly observed in the invasive component of pancreatic cancer, but not in the noninvasive component even within the same specimen." (PMID 25883990, 2015). "The use of rat N-ERC/mesothelin as a serum marker lies in its ability to distinguish between rats with or without pancreas cancer without opening the abdominal cavity." (PMID 25347530, 2014). "As we only collected the plasma samples on a single time point, we are not able to describe the change of plasma levels of MSLN and IL-10 during the progression of pancreatic cancer based on our data." (PMID 24520352, 2014). "In animal models, the induction of anti-Mesothelin CD8+ T cell responses resulted in the reduction in tumour volume and prolonged survival in an orthotopic PC mouse model, suggesting that MSLN is a tumour rejection antigen for pancreatic carcinoma." (PMID 24520352, 2014). "This verifies our hypothesis that MSLN can promote EMT, thus metastasis of pancreatic cancer." (PMID 38628720, 2024). "To investigate the effect of CD83 overexpression on antitumor efficacy of CAR-T cells in vivo, we infused mesothelin-targeting CAR-T cells with or without ectopic expression of CD83 into NSG mice that were subcutaneously inoculated with the mesothelin-expressing pancreatic cancer cell line AsPC-1." (PMID 36906640, 2023). "However, MSLN is also expressed in tumours that emerge from tissues that do not normally express MSLN, such as pancreatic cancer." (PMID 37040900, 2023). "MSLN was detected in 77.4% (n = 31) of the PaC tissues and in 10% of the control tissues (n = 10), which corresponded to the non-tumor tissue adjacent to the pancreatic tumor." (PMID 36009489, 2022). "However, we have shown that stable overexpression of mesothelin in a pancreatic cancer cell line did not increase cell proliferation or anchorage- independent growth in vitro, suggesting that mesothelin is not necessarily a tumor progression factor." (PMID 29474384, 2018). "Here, we further studied the immunogenicity of chimeric murine MSLN-virus-like particles (mMSLN-VLPs), their ability to break tolerance to mMSLN, a self-antigen, and deciphered the mechanism of immune responses elicited by mMSLN-VLP immunization using a pancreatic cancer (PC) mouse model." (PMID 23874581, 2013). "Mesothelin (MSLN) is a protein highly expressed on the surface of various solid tumors, including pancreatic cancer cells, but rarely or not at all on normal cells." (PMID 40705122, 2025). "The MSLN/CD3 bsAb had specific binding to the MSLN-positive pancreatic cancer cell lines KLM-1, T3M4 and the MSLN-highly expressing H9 cells, but not to the MSLN-negative A431 cells." (PMID 39995672, 2025). "This was not due to downregulation of mesothelin because its expression was confirmed ex vivo; however, PET imaging using 89Zr-anti-meosthelin ADC showed reduced tumor uptake in the unresponsive pancreatic cancer models." (PMID 37880707, 2023). "There was significant anti-tumor activity against pancreatic cancer cell lines and xenograft tumor models expressing both CEA and MSLN, and there was a lack of T-cell activation in the presence of just one antigen." (PMID 36290818, 2022). "The pancreatic cancer cell lines KP2, KP3, ASPC1, and SUIT2 expressed mesothelin, whereas PANC1 and KP4 did not." (PMID 30140382, 2018). "Immunofluorescence confirmed the expression of mesothelin in both pancreatic cancer cell lines BxPC-3 and JoPaca-1, no expression was detected in the normal cell line HPDE c7, showing the tumour specific expression of mesothelin." (PMID 23152778, 2012). "Interestingly, although the four pancreatic cancer cell lines examined showed appreciable mesothelin expression in vitro, the response to the ADC varied in vivo and was independent of the expression levels of mesothelin." (PMID 37880707, 2023).